UBQLN4 (ubiquilin 4)
Diseases named in the same sentence as UBQLN4 in open-access papers (continued):
Sharing a sentence is not in itself a finding about the gene and the disease.
tumor (16 papers, 2019 to 2024). "The impact of UBQLN4 on tumor-associated signaling pathways was assessed using the path scan intracellular signaling array." (PMID 38969831, 2024). "Among 13 tumor types, high expression of UBQLN4 was associated with high TMB, predicting a better response to immunotherapy." (PMID 34539785, 2021). "The tumor mutator phenotype and UBQLN4 expression level, critical indicators of genomic instability, are significantly correlated with the GILncSig." (PMID 34840594, 2021). "In this study, overexpression of Ubqln4 caused a G1 phase arrest, which supported a tumor suppressor function of Ubqln4." (PMID 29899380, 2019). "Additionally, the GILncSig is strongly associated with the phenotype of the tumor mutator and the UBQLN4 expression level in LUAD, both of which are essential markers of genomic instability." (PMID 34866362, 2022). "More and more studies have shown that UBQLN4 is a vital tumor-associated gene." (PMID 34930912, 2021). "Our results found that UBQLN4 was positively correlated with methyltransferase-related genes in most tumors, and UBQLN4 methylation was associated with UBQLN4 mRNA, indicating the correlation between UBQLN4 methylation and tumor genetics." (PMID 34539785, 2021). "Moreover, UBQLN4 mRNA was significantly correlated with immune checkpoints, tumor mutational burden (TMB), microsatellite instability (MSI), and mismatch repair (MMR)." (PMID 34539785, 2021). "Loss of function experiments showed that suppression of UBQLN4 could significantly inhibit cell viability, proliferation rate, invasion ability and tumor formation ability in vitro and in vivo." (PMID 31911755, 2020). "Though tumor heterogeneity remains a major cause of the prognostic and therapeutic difficulty in the management of advanced stages of cancer, clonal transcriptomic biomarkers such as UBQLN4 upregulation can be very useful in precision oncology treatment decisions." (PMID 36291176, 2022). "In addition, we confirmed that the somatic mutation count, tumor mutation burden, and the expression of UBQLN4, which were ascertainably associated with genomic instability, were significantly correlated with the GILncSig, indicating its reliability as a measurement of the genomic instability." (PMID 34712264, 2021). "Conversely, the tumor volume and weight were significantly larger in the UBQLN4 overexpression group (plvx-UBQLN4) compared to the control group (plvx-NC), **p< 0.01." (PMID 38969831, 2024). "In vivo tumorigenesis experiments were conducted to further investigate the influence of UBQLN4 on tumor formation." (PMID 38969831, 2024). "Subsequently, we conducted qRT-PCR and WB experiments on tumor tissues obtained from mice to investigate the expression levels of UBQLN4, PI3K, p-PI3K, AKT, and p-AKT." (PMID 38969831, 2024). "Consistent with our previous in vitro cell experiments, we observed that the tumor volume and weight were significantly smaller in the UBQLN4 knockdown group (sh-UBQLN4) compared to the control group (sh-NC), **p < 0.01." (PMID 38969831, 2024). "The results revealed that in the sh-UBQLN4 group, both UBQLN4 mRNA and protein levels in tumor tissues decreased, as did the levels of p-PI3K and p-AKT proteins." (PMID 38969831, 2024). "Of note, UBQLN4 amplification and overexpression were observed in individual tumor types from patients diagnosed even with AJCC stage I." (PMID 36291176, 2022). "Albendazole stimulates tumor immune function by reducing UBQLN4 expression and, as a result, facilitating PD-L1 protein degradation." (PMID 35907881, 2022). "To investigate the clinical application potential of strategies targeting UBQLN4/PD-L1, we compared the expression levels of UBQLN4/PD-L1 between paired tumor and normal tissue samples across 16 cancer types from The Cancer Genome Atlas (TCGA)." (PMID 35577504, 2022). "DNA amplification was identified as the main mechanism promoting UBQLN4 upregulation in multiple cancers, even in the early phases of tumor development." (PMID 36291176, 2022).
tumor (continued). "Using CRISPR screen datasets, UBQLN4 was identified as a common essential gene for tumor cell viability in 81.1% (860/1,060) of the solid tumor derived cell lines." (PMID 36291176, 2022). "To further explore the relationship between UBQLN4 and tumor microenvironment, we estimated the correlation between UBQLN4 expression, CNV, methylation, and various immune cells in different tumors." (PMID 34539785, 2021). "After integrating tumor and normal tissue samples of TCGA and GTEx databases, UBQLN4 mRNA was significantly upregulated in DLBC and THYM compared with normal tissues (P < 0.05)." (PMID 34539785, 2021). "MTS and plate colony formation experiments showed that UBQLN4 increased CRC cell proliferation, consistent with the result that UBQLN4 expression correlated with tumor size." (PMID 34930912, 2021). "Compared to the LV-NC group, the LV-Si-UBQLN4 group had a much smaller mean tumor volume and tumor weight, manifesting that targeted knockdown of UBQLN4 expression effectively inhibited tumor proliferation in vivo." (PMID 34930912, 2021). "Subcutaneous tumor formation analysis in nude mice was conducted to further verify the role of UBQLN4 in HCC progression in vivo." (PMID 31911755, 2020). "Suppression of UBQLN4 inhibits cell viability, proliferation, invasion and tumor formation abilities of HCC cells by suppressing the activation of the wnt-β-catenin signaling pathway." (PMID 31911755, 2020). "By conducting cell function experiments, we observed that UBQLN4 overexpression reversed tumor suppressive roles of miR-370 in HCC cells." (PMID 31911755, 2020). "Ubiquilin -4 acts as a tumor suppressor during the progression of gastric cancer by inducing cell cycle arrest and senescence via the extracellular signal-regulated kinases (ERK) signaling pathway." (PMID 31911755, 2020). "Through the following cell function experiments, we observed that miR-370 expression inhibited the viability, clonal formation and invasion abilities of HCC cells, whereas overexpression of UBQLN4 partially reversed tumor suppressive functions of miR-370." (PMID 31911755, 2020). "Ubiquilin-4 (UBQLN4) is a member of the ubiquitin–proteasome system that is usually upregulated in many tumor cells." (PMID 31911755, 2020). "Suppression of UBQLN4 inhibited tumor formation, proliferation, and invasion in vitro and in vivo by regulating wnt-β-catenin pathway." (PMID 31911755, 2020). "The major finding of this study is that Ubqln4 acts as a tumor suppressor in the context of GC by inducing cell cycle arrest and senescence." (PMID 29899380, 2019). "Xenograft tumors from MKN45 stable cell lines overexpressing Ubqln4 had smaller mean tumor volume and weight compared with tumors from control cells." (PMID 29899380, 2019). "Our study establishes a novel tumor-suppressive function for Ubqln4 in GC that involves regulation of p21 through multiple pathways." (PMID 29899380, 2019). "The suppressive function of Ubqln4 on cell proliferation was further examined using tumor growth assays." (PMID 29899380, 2019). "H1299 cells transfected with plvx-NC and plvx-UBQLN4, as well as A549 cells transfected with sh-NC and sh-UBQLN4, were implanted into the left (plvx-NC/sh-NC) and right (plvx-UBQLN4/sh-UBQLN4) inner thighs of nude mice to establish xenograft tumor models for subsequent experiments." (PMID 38969831, 2024). "Increased levels of UBQLN4 in tumor cells correlate with heightened genomic instability." (PMID 39440050, 2024). "Notably, PYGO2, UBQLN4, and ANXA1 have been associated with responsiveness to tumor immune checkpoint blockade (ICB) therapy, while B4GAL and MDM2 are implicated in regulating CD8 + T cell function and tumor growth." (PMID 38834869, 2024). "Next, we assessed the prognostic significance of UBQLN4 mRNA levels across different tumor types." (PMID 36291176, 2022). "Additionally, UBQLN4 overexpression reversed tumor suppressive functions mediated by miR-370 in HCC." (PMID 36291176, 2022).
tumor (continued). "Pan-cancer tumor tissues showed higher UBQLN4 protein levels than paired adjacent normal tissues." (PMID 36291176, 2022). "Moreover, we observed that patients with high UBQLN4 and PD-L1 expression in the tumor region had better progression-free survival (PFS; median PFS 10 months vs 2 months, log-rank test, p<0.001) after anti-PD-1 treatment." (PMID 35577504, 2022). "Our study found that higher expression of UBQLN4 was significantly correlated with lower immune and stromal scores in most tumors, suggesting that UBQLN4 may participate in tumor progression by regulating the immune microenvironment." (PMID 34539785, 2021). "In addition, the significant correlation between GILncSig and tumor mutator phenotype, TMB, and UBQLN4 indicated that GILncSig can serve as a good indicator of genomic instability." (PMID 34712264, 2021). "However, the research on UBQLN4 in tumor treatment is still limited, and further research is urgent." (PMID 34539785, 2021). "Since DNA damage is an important mechanism of radiotherapy and chemotherapy, it may be one of the mechanisms of UBQLN4 affecting tumor therapy." (PMID 34539785, 2021). "The present study demonstrated for the first time that UBQLN4 is overexpressed in advanced HCC tissues, and high expression of UBQLN4 is associated with poor TNM stage, poor histological grade, large tumor size, vascular invasion and poor overall and disease-free survival rates." (PMID 31911755, 2020). "Next, expression levels of UBQLN4 and Ki67 were evaluated in tumor tissues of nude mice." (PMID 31911755, 2020). "Collectively, the results of the present study showed that UBQLN4 overexpression could partially reverse the anti-tumor effects of miR-370 in HCC cells." (PMID 31911755, 2020). "Overexpression of UBQLN4 reversed tumor suppressive function of miR-370." (PMID 31911755, 2020). "Furthermore, our results showed that UBQLN4 was downregulated by miR-370, which acted as a tumor suppressor gene in HCC progression." (PMID 31911755, 2020). "Besides, high expression of UBQLN4 was associated with poor TNM stage, poor histological grade, large tumor size, vascular invasion and poor overall survival time." (PMID 31911755, 2020). "On the basis of our results showing a tumor-suppressive influence of Ubqln4 on GC cells, we next evaluated whether the effects of Ubqln4 are mediated by p21." (PMID 29899380, 2019). "Additionally, UBQLN4 can suppress the progression of GC by preventing tumor cell proliferation." (PMID 34761007, 2021). "UBQLN4 belongs to the UBQLN, participating in various cellular processes and often exhibiting over-expression in many tumor cells." (PMID 38969831, 2024). "Our findings reveal that UBQLN4 promotes the proliferation and invasion of NSCLC cells by activating the PI3K/AKT pathway, thereby facilitating tumor development." (PMID 38969831, 2024). "Thirty-two patients (64%) showed higher expression of UBQLN4 in CRC tissues than in matched ANTs, and UBQLN4 expression increased as the tumor progressed." (PMID 34930912, 2021). "Both tumor and normal mucosa tissues showed positive and negative staining of Ubqln4." (PMID 29899380, 2019).
cancer (13 papers, 2019 to 2024). A tumor composed of atypical neoplastic, often pleomorphic cells that invade other tissues. "We further performed survival analyses and demonstrated that high UBQLN4/PD-L1 scores were associated with worse survival in most cancer types from TCGA, the patients of whom were mainly treated with chemotherapy or targeted therapy." (PMID 35577504, 2022). "In contrast, we found that the expression levels of UBQLN4/PD-L1 were associated with better survival in most cancer types from the public ICB cohort." (PMID 35577504, 2022). "We evaluated the biologic and oncologic significance of UBQLN4 in pan-cancer at multiomics level, such as expression, mutation, copy number variation (CNV), methylation, and N6-methyladenosine (m6A) methylation." (PMID 34539785, 2021). "Recently, it was reported that ubiquilin 4 (UBQLN4) alteration was associated with genomic instability in some cancers." (PMID 34539785, 2021). "We performed a gene set enrichment analysis (GSEA) on the transcriptome data from all CRC patients in TCGA database to explore the molecular mechanism underlying the cancer-promoting effect of UBQLN4." (PMID 34930912, 2021). "Consequently, increased UBQLN4 levels were associated with cisplatin resistance and Olaparib sensitivity in pan-cancer cell lines." (PMID 36291176, 2022). "UBQLN4 was associated with poor prognosis across multiple cancer types." (PMID 36291176, 2022). "Cancer cell lines with high UBQLN4 mRNA levels were associated with a better Olaparib response." (PMID 36291176, 2022). "Our analysis showed that UBQLN4 mRNA levels are associated with current chemotherapies resistance in cancer cells such as cisplatin resistance and Olaparib sensitivity in many different cancer cell lines." (PMID 36291176, 2022). "The aim of this study is to perform a comprehensive pan-cancer analysis of UBQLN4 using large cohorts of cancer patient datasets." (PMID 36291176, 2022). "To summarize, UBQLN4 mRNA levels are upregulated in 20 of 32 cancer types, resulting in the upregulation of UBQLN4 at protein levels." (PMID 36291176, 2022). "Data integration showed that in patients with LIHC, BRCA, LUAD, UCEC, SKCM, and CESC cancer types, UBQLN4 gene amplification positively correlated with enhanced UBQLN4 mRNA levels and is a prognostic factor for OS in all stages." (PMID 36291176, 2022). "Taken together, these results indicate that UBQLN4 plays an essential role in cancer cell lines growth and perpetuation suggesting that genomic alterations promoting UBQLN4 mRNA levels are also conserved in in vitro models." (PMID 36291176, 2022). "Our findings highlight the utilities of UBQLN4 as a significant pan-cancer theranostic factor and a precision oncology biomarker for DDR-related drug resistance." (PMID 36291176, 2022). "The chromosomal region 1q22, which contains UBQLN4, was identified as the frequently amplified chromosome region in all these cancer types (FDR q-value < 0.0001)." (PMID 36291176, 2022). "Expression levels of miR-370 showed statistically significant but only small positive correlation values with UBQLN4 mRNA levels in the pan-cancer comparisons (Pearson correlation coefficient = 0.18, p < 0.001)." (PMID 36291176, 2022). "Taken together, these data demonstrated that the expression of UBQLN4/PD-L1 is a promising cancer biomarker and potential predictor for assessing the efficacy of anti-PD-1 therapy in the clinic." (PMID 35577504, 2022). "In silico analyses were performed using TCGA and GTEx databases to explore how frequent UBQLN4 upregulation was observed in different types of cancers respective to their normal cell origin." (PMID 36291176, 2022). "The results showed that cancer cell lines with high UBQLN4 mRNA levels had higher cisplatin AUC values in all cancer types." (PMID 36291176, 2022).
cancer (continued). "Solid tumor tissues from 32 cancer types and adjacent normal tissues from 27 cancer types in the TCGA databases were screened and analyzed to determine the frequency of UBQLN4 copy number variation (CNV)." (PMID 36291176, 2022). "Recently, it was reported that the alteration of UBQLN4 resulted in genomic instability through affecting DNA damage repair, which is one of the most important features of cancers." (PMID 34539785, 2021). "We utilized Oncomine, TCGA, and GTEx databases for differential expression analysis of UBQLN4 mRNA in various cancer types." (PMID 34539785, 2021). "The heatmap indicated that UBQLN4 mRNA was positively related to transmethylase-related genes in most cancers, and with the highest correlation score in GBM." (PMID 34539785, 2021). "Subsequently, the prognostic significance of UBQLN4 CNV was also analyzed in pan-cancer using GSCA database." (PMID 34539785, 2021). "Our results indicated that UBQLN1 and UBQLN4 played a similar role in some cancer-related pathways, such as apoptosis, cell cycle, EMT, hormone ER, PI3K/AKT, RAS/MAPK, and TSC/mTOR." (PMID 34539785, 2021). "We found that UBQLN4 mRNA and protein were overexpressed in most cancer types, and the expression, mutation, CNV, and methylation of UBQLN4 were associated with the prognosis of some cancers." (PMID 34539785, 2021). "According to the data from TCGA database, UBQLN4 is amplified in many cancers, the red part represents amplification, the green part represents mutation, and the blue part represents deletion." (PMID 34245648, 2021). "In this study, we performed comprehensive analyses of UBQLN4 in pan-cancer based on multiomics data, and UBQLN4 was identified as a promising immune and prognostic molecular biomarker." (PMID 34539785, 2021). "Gradually, the role of UBQLN4 in cancers attracted increasing attention, although theories behind are premature." (PMID 34539785, 2021). "Actually, the mechanism of UBQLN4 in cancers was less explored compared with other members in UBQLNs family." (PMID 34539785, 2021). "Fifthly, we explored the potential functions and pathways of UBQLN4 in pan-cancer based on CancerSEA and GSCA database." (PMID 34539785, 2021). "Ultimately, we concluded that UBQLN4 was a promising prognostic biomarker of immune-related therapy in pan-cancer." (PMID 34539785, 2021). "Survival analysis of the TCGA mesothelioma cancer database using GEPIA suggested that cancer patients with low levels of UBQLN4 survived significantly longer than those with high levels of UBQLN4." (PMID 34245648, 2021). "More importantly, the high-risk patients were associated with decreased UBQLN4 expression, higher accumulation of immune cells, lower Titin (TTN) mutation frequency, worse immunotherapy efficacy, and cancer-associated pathways." (PMID 34761007, 2021). "Our results were consistent with that UBQLN4 was overexpressed in mostly all cancer types compared with normal tissues, which was also verified at proteomics." (PMID 34539785, 2021). "Similar effects of apoptosis, cell cycle, EMT, hormone ER, PI3K/AKT, RAS/MAPK, and TSC/mTOR were found between UBQLN1 and UBQLN4 in pan-cancer." (PMID 34539785, 2021). "CancerSEA database was performed to identify the functional state of UBQLN4 across various cancers at the single-cell level." (PMID 34539785, 2021). "The heatmap indicated that UBQLN4 was positively related to UBQLN1 and UBQLN2 in most cancers with statistical significance, while few correlations were found between UBQLN4 and the remaining two members (UBQLN3 and UBQLNL)." (PMID 34539785, 2021). "GSEA indicated that the NES of the Wnt/β-catenin signaling pathway was 2.45 and the false discovery rate (FDR) q value <0.001, indicating that UBQLN4 is likely to exert its cancer-promoting effect via activating the Wnt/β-catenin signaling pathway." (PMID 34930912, 2021). "Immunochemistry, real-time PCR, and western blotting were used to evaluate the expression levels of UBQLN4 in cancer tissues." (PMID 31911755, 2020).